CD4 (CD4 molecule)
Diseases named in the same sentence as CD4 in open-access papers (continued):
Sharing a sentence is not in itself a finding about the gene and the disease.
encephalitis (continued). "The inflammatory infiltrates in the brain parenchyma of the VSBV-1 encephalitis patients mainly consisted of CD4+ and CD8+ T cells, accompanied by neutrophils and macrophages, and a few B cells." (PMID 31107210, 2019). "A recent study in mice showed that depletion of CD4 or CD8 cells led to increases in the frequency of encephalitis." (PMID 31220182, 2019). "Using the VSV encephalitis mouse model, we determined that CD4 T cell help also rendered virus-specific CD8 T cells susceptible to systemic CD8 T cell depletion." (PMID 30372487, 2018). "In experimental autoimmune encephalitis, the production of GM-CSF by CD4+ T cells is required to induce encephalitis, while GM-CSF secreted by RA synovial CD4+ T cells promotes the differentiation of inflammatory dendritic cells." (PMID 30157949, 2018). "Using the mouse polyomavirus (MuPyV) encephalitis model, we demonstrate that CD4 T cells regulate development of functional antiviral brain-resident CD8 T cells (bTRM) and renders their maintenance refractory to systemic CD8 T cell depletion." (PMID 30372487, 2018). "The importance of CD4 T cells for homeostasis of virus-specific CD8 T cells during a persistent viral encephalitis has clear clinical ramifications for establishing durable immunosurveillance of persistent CNS infections." (PMID 30372487, 2018). "In this study, we investigated the importance of CD4 T cell availability to CD8 TRM development during persistent viral encephalitis." (PMID 30372487, 2018). "CCR5 is also a key mediator to recruit CD4+Foxp3+ Tregs known as regulatory CD4+ T cell subset to dampen exacerbated inflammation such as viral encephalitis." (PMID 27439902, 2016). "Our results suggest that CCR5 regulates the progression of viral encephalitis via governing a timely and an appropriate CNS infiltration of CD4+Foxp3+ Tregs and ultimately promoting survival of hosts suffering severe neuroinflammation." (PMID 27439902, 2016). "Although neither has been directly implicated in lymphocyte recruitment to the lungs, TIMP-1 does appear to regulate CD4+ T cell migration into brain parenchyma in a murine model of viral encephalitis, independently of MMPs." (PMID 26243260, 2015). "We observed that this coimmunization significantly inhibited the formation of encephalitis by inducing a group of iTregs to inhibit the migration of CD4+ T cells into the brain." (PMID 24987466, 2014). "Here we extend these results to mice with coronavirus-induced encephalitis and show that Tregs specific for a virus-specific CD4 T cell epitope are highly activated and protective." (PMID 25102154, 2014). "We recently showed the presence of both epitope M133-specific Tregs (M133 Treg) and conventional CD4 T cells (M133 Tconv) in the brains of mice with coronavirus-induced encephalitis." (PMID 25102154, 2014). "Encephalitis patients had lower CD4 (218/μl, p = 0.029) and CD8 (200/μl, p = 0.012) T cell counts than controls." (PMID 23967232, 2013). "Next, Thomas Korn from Munich gave a presentation on the consequences of VLA-4 blockade on the function of different CD4+ positive T helper cell subsets in a mouse model of acute viral encephalitis." (PMID 24330587, 2013). "In summary, our data demonstrate a novel MMP-independent role of TIMP-1 in regulating CD4+ T cell migration across the glia limitans during viral encephalitis." (PMID 24156369, 2013). "Following VSV infection, a rapid CD4+ T cell-dependent IgG formation is necessary to prevent lethal encephalitis." (PMID 18000535, 2007). "However, viral encephalitis induces CD4+ and CD8+ T cell infiltration and more Lgals3/MAC2-expressing macrophages surrounding dense-core Aβ plaques, which appear more compacted in JHMV-infected 5xFAD brains compared to uninfected 5xFAD controls." (PMID 42124663, 2026). "A recent study also confirmed that the NSs-deleted RVFV strain is capable of causing encephalitis in the absence of CD4+ T cells working synergistically with monocytes and CD8+ T cells." (PMID 37764982, 2023).
encephalitis (continued). "Furthermore, the depletion of CD4+ or CD8+ T lymphocytes drastically reduced the vaccine-based protection observed in the encephalitis model." (PMID 32384822, 2020). "Although the role of CD4+Foxp4+ Tregs in flavivirus encephalitis remains elusive, CCR5-dependent recruitment of CD4+Foxp3+ Tregs may play certain roles in the control of encephalitis progression caused by flavivirus infection." (PMID 27439902, 2016). "A putative correlation between CD4+Foxp3+ Treg levels and the outcome of infectious disease has been reported in WNV encephalitis because patients with symptomatic infection have lower CD4+Foxp3+ Treg frequencies throughout the infection compared to asymptomatic patients." (PMID 27439902, 2016). "Therefore, CCR5 is involved in the putative role of CD4+Foxp3+ Tregs in severe flavivirus-induced diseases, such as encephalitis and hemorrhagic fever." (PMID 27439902, 2016). "Presumably, CCR5-dependent recruitment of CD4+Foxp3+ Tregs may affect the progression of viral encephalitis via their regulatory function." (PMID 27439902, 2016). "Recent work implicates CD4+Foxp3+ Tregs in the control of neuroinflammation caused by WNV32, wherein peripheral expansion of Treg was associated with mild inflammation, but reduced Treg levels were associated with WNV encephalitis." (PMID 26626303, 2015). "Their use in the context of encephalitis or other infections would allow targeting of pathogenic CD4 T cell responses without generally suppressing the protective components of the immune response." (PMID 25102154, 2014). "In contrast, primary CTL responses induced in noninfectious conditions by minor Ags, and cell-associated and protein-triggered immunizations, and also CTL responses in infectious diseases, such as Herpes simplex (HSV), Viral encephalitis and Vaccinia virus, heavily depend on CD4+ T cell signals." (PMID 23071696, 2012). "Notably, GM-CSF+ CD4+ T cells, which have been linked to neuroinflammation in other models, such as EAE and viral encephalitis, may play a role in BLA’s vulnerability." (PMID 41301925, 2025). "Neuro-COVID patients exhibit depleted CD4+ T cells and dedifferentiated monocytes in their CSF, accompanied by increased interferon signatures that are indicative of a significant immune response, albeit less pronounced than that observed in virus-induced encephalitis." (PMID 38793710, 2024). "Depletion of CD4+ and/or CD8+ T cells was shown to impede VSV containment within the OB and to promote development of lethal encephalitis in infected mice, suggested that T cells exert antiviral functions during CNS infection." (PMID 39153993, 2024). "Depleting C57Bl/6 mice of CD4+ and CD8+ T cells increased the frequency of encephalitis, supporting that these cell types contribute to the prevention of disease." (PMID 38543848, 2024). "In the encephalitis model of infection, long-term protective immunity is mediated by CD8 T cells, with the CD4 T cell population providing important help." (PMID 36883950, 2023). "This is consistent with fatal encephalitis seen in our TMEV-infected T-bet-tg mice whose anti-viral antibody and CD4+/CD8+ T cell responses were significantly decreased." (PMID 28874814, 2017). "Using classical cell surface markers and hierarchical gating, we quantified granulocytes, NK-cells, monocytes, B cells, CD4+ T cells and CD8+ T cells in blood samples of 11 mice tamoxifen-induced post-encephalitis mice and 10 healthy control mice after completion of the 10-months follow-up period." (PMID 40579402, 2025). "Brain CD4+ and CD8+ T cells are PD-1high during mouse polyomavirus (MuPyV) encephalitis." (PMID 41409145, 2025). "Early SHIV/NHP models with less overt encephalitis failed to consistently maintain CD4 and CCR5 tropism, limiting their biological relevance in the CNS." (PMID 37563642, 2023). "In the encephalitis models, the CD8+T inhibit the expansion of CD4+T cells via cell–cell contact." (PMID 37542271, 2023).
encephalitis (continued). "At the same time, CD4+ T cells and neutrophils were significantly augmented, accompanied by the alteration of cytokine expression with the administration of BM‐EVs, reinforcing the immunomodulatory role of EVs during JEV‐induced encephalitis." (PMID 36479206, 2022). "CD4 T cells are shown to protect mice from HSV-1 infection, as mice lacking CD4 T cells are susceptible to virus-induced encephalitis, when compared to WT mice." (PMID 35277184, 2022). "A recent study using macaques infected with a neuropathogenic SIV clone, CL757, that results in progression to SIV-induced encephalitis (SIVE) in 50% of those infected, showed increased numbers of memory CD4+ T cells (mCD4s) and macrophages in the brains of macaques with SIVE." (PMID 33727362, 2021). "Although not a direct comparison, encephalitis deaths in CD4-depleted inbred mice have been seen as late as 36 days post-infection with ∆NSs RVFV." (PMID 32973712, 2020). "When mice are depleted of both CD4+ and CD8+ T cells, the incidence of encephalitis increases." (PMID 32850501, 2020). "Mice depleted of CD4+ T cells and infected with attenuated RVFV, which is normally not able to generate disease, develop encephalitis, associated with lower virus-specific humoral and T-cell memory responses." (PMID 32850501, 2020). "Similarly, in our model of viral encephalitis, PSA induced both FoxP3+CD39+Tregs and also FoxP3−CD39+CD73+CD4+ and CD73+CD8+ regulatory T cells." (PMID 31089128, 2019). "Thus, we found that the link between CD4 T cell help and establishment of CD8 bTRM applies to both MuPyV and VSV encephalitis." (PMID 30372487, 2018). "Taken together, TMEV-infected mice generally develop fatal acute encephalitis when the mice have neither antibody (which requires CD4+ T cell help) nor CD8+ T cell responses." (PMID 28874814, 2017). "Moreover, children in the HFMD with encephalitis group showed further reduction in the CD3+ and CD3+CD4+ cell subsets and elevation in the CD3−CD19+ cell subset compared to children in the uncomplicated HFMD group." (PMID 24939221, 2014). "Thus, CNS CD4+ and CD8+ T-cell responses 15 dpi differ dramatically from abundant reactive glial cell levels, which suggest a selective role for glial cell responses in acute phases of POWV encephalitis (43, 44, 47, 58, 59, 79, –, 84)." (PMID 39087762, 2024). "Although one patient was HIV infected, she had maintained a normal CD4 count and undetectable HIV RNA levels in her blood for years, under efficient antiretroviral therapy, which she diligently adhered to, including throughout the hospitalisation for encephalitis." (PMID 39200800, 2024). "In WNV encephalitis, the disease is dependent on nitric oxide-producing monocytes/macrophages infiltrating the CNS parenchyma, while, similar to our results with the Rag1−/− mice, CD4+ and CD8+ T cells do not contribute significantly to pathology in the absence of peripheral infection." (PMID 31511023, 2019). "Because an increased number of CD4+CD25+Foxp3+ Treg cells is correlated with milder forms of encephalitis caused by flavivirus infection, this finding suggests that IFN-γ produced from CD4+ Th1 cells can affect the progression of JE without changing the number of CD4+CD25+Foxp3+ Treg cells." (PMID 26597582, 2015). "This conclusion is more indirectly supported by the low observed frequency of clonal CSF CD4+ T cells, and the histological absence of TLS despite very few LGI1 or CASPR2 antibody encephalitis brain specimens having been studied." (PMID 38319973, 2024). "There were statistically significant differences in CD3+, CD3+CD4+ and CD3−CD19+ cell subsets, but not in Notch ligand expression, between the uncomplicated HFMD and HFMD with encephalitis groups." (PMID 24939221, 2014). "16.4% of these patients with median CD4 counts 43.3cells/ul presented with CMV viremia without any end-organ diseases, while 4.2% presented with CMV retinitis and 1.1% with encephalitis with median CD4 counts 63.5 and 14.2cells/ul, respectively." (PMID 24204583, 2013).
encephalitis (continued). "Use of small interfering RNA (si-RNA) inhibits the expression of RORγ on myelin-specific CD4 T cells; however, this does not reduce the severity of adoptively transferred EAE, indicating that in terms of encephalitis CD4 T cells, RORγt is not an effective therapeutic target." (PMID 30974919, 2019). "However, CD4+ T cells can also control WNV viral loads and encephalitis independent of B and CD8+ T cells." (PMID 30087337, 2018). "Unlike earlier works on flavivirus encephalitis, the present study showed that the JEV burden in the extraneural tissue and CNS of Ccr5+/+ mice was similar to that in Ccr5−/− mice, with transiently and early increased CNS infiltration of NK and CD4+ cells, but not CD8+ T cells, in Ccr5+/+ mice." (PMID 27439902, 2016).
T cell deficiency (85 papers, 2006 to 2026). "While CD4+ T cell deficiency is a known factor responsible for CMV replication in immunocompromised individuals, CMV viremia is almost always undetectable in PLWH on ART when their blood CD4+ T cell counts are restored." (PMID 40920867, 2025). "CD4 + T-cell deficiency and NK cell deficiency occur in lipopolysaccharide-responsive beige-like anchor (LRBA) protein deficiency, causing immunosuppression." (PMID 38719908, 2024). "Nevertheless, HIV-infected individuals have many immunological abnormalities in addition to CD4+ T cell lymphopenia, preventing the generalization of direct mechanistic links of CD4+ T cell deficiency with specific infectious diseases." (PMID 38557723, 2024). "In mouse models of ischemia and nephrotoxicity, CD8+ T cell deficiency provided less protection compared to CD4+ T cell deficiency.Activated CD4+ T cells differentiate into various subsets, each with distinct effects." (PMID 39857243, 2024). "The importance of CD4 + T cells in atherogenesis has been highlighted by animal studies showing that transfer of CD4 + T cells aggravates, whilst CD4 + T cell deficiency attenuates atherosclerosis." (PMID 38368442, 2024). "While each of the patients with inherited CD4 deficiency displayed an infectious phenotype, it was, however, milder than that reported for people with CD4+ T cell deficiency due to HIV infection, HLA class II deficiency, or idiopathic CD4+ T cell lymphopenia." (PMID 38557723, 2024). "Her kidney function was normal, urinalysis revealed nephrotic proteinuria, the blood count showed apparent leukopenia (3.5 × 109/L) and immunologic examination revealed significant T-cell deficiency with decreased CD4 and CD8 cells." (PMID 36658659, 2023). "To assess the role of CD4+ T cells in TAS2010-induced immunity, we used two models of CD4+ T cell deficiency applied at the start of primary (vaccination) or secondary (challenge) infection, respectively." (PMID 37733817, 2023). "An animal model of T cell deficiency was achieved by the administration of 200 μg/mouse anti-CD4 antibody and/or 100 μg/mouse anti-CD8 antibody 9 days prior to the first vaccination and weekly thereafter during the course of the experiment." (PMID 36719231, 2023). "In this study, we present the immune mechanisms by which SGs and GXM provide complete host protection in condition of CD4+ T cell deficiency." (PMID 36229573, 2022). "The MHCII-/- mice used in these studies have a complete CD4+ T cell deficiency, but the CD4+ T cell levels of patients with cryptococcal disease are variable." (PMID 36248898, 2022). "To identify potential responsible molecular etiologies underlying CD4+ T cell deficiency-mediated LGG formation, we performed transcriptomal analysis on whole brainstems of wild type and Rag1−/− mice." (PMID 35986378, 2022). "In conclusion, our results suggest that C. neoformans Δsgl1 stimulates γδ T cells to produced IFNγ and IL-17A through a host-protective interaction between TLR2 and GXM/SGs, an immune mechanism that is still preserved in condition of CD4+ T cell deficiency." (PMID 36229573, 2022). "In previously vaccinated mice, administration of HK C. neoformans Δsgl1 post WT challenge significantly decreased the lung fungal burden post challenge, even during CD4+ T cell deficiency." (PMID 35615354, 2022). "We accidentally observed CD4+ T-cell deficiency in mice that were obtained from long-term homozygous breeding of lc3b knockout mice." (PMID 35309308, 2022). "This raises an intriguing potential link between CD4 T cells deficiency and decreased eNOS expression in 4 weeks PP ICAs." (PMID 34220551, 2021). "We showed among the patients with CD4+ T cell deficiency on admission, the increase in CD4+ was more obvious in the HDIVC group than in the control group." (PMID 33967773, 2021). "In our study, 12 out of 55 patients in the HDIVC group and 18 out of 55 patients in the control group had CD4+ T cell deficiency on admission." (PMID 33967773, 2021).